PIK3C2B (phosphatidylinositol-4-phosphate 3-kinase catalytic subunit type 2 beta)
Diseases named in the same sentence as PIK3C2B in open-access papers (continued):
Sharing a sentence is not in itself a finding about the gene and the disease.
cancer (18 papers, 2013 to 2025). A tumor composed of atypical neoplastic, often pleomorphic cells that invade other tissues. "This functional dichotomy—where PIK3C2B overexpression drives cancer progression while its deficiency promotes neuronal hyperexcitability—highlights the context-dependent nature of PI3K–C2β signaling in human diseases." (PMID 41362647, 2025). "A recent study also reported that PIK3C2B gene single-nucleotide polymorphisms (SNP) is associated to cancer risk susceptibility." (PMID 23658859, 2013). "In addition to detecting the PIK3CA H1047R mutation, this WGS confirmed the variant detected by the cancer gene panel in the PIK3C2B gene and demonstrated that it was germline." (PMID 35787784, 2022). "Different studies linked PIK3C2B to cancer cell migration and lamellipodia/filopodia formation." (PMID 30884740, 2019). "The dual enhancement of OXPHOS and glycolysis by PIK3C2B challenges the classical “Warburg effect” paradigm, where cancers prioritize glycolysis even under aerobic conditions." (PMID 41362647, 2025). "Clinically, our survival data corroborate prior cancer analyses identifying PIK3C2B amplification as a prognostic marker." (PMID 41362647, 2025). "PIK3C2B has a well-described role in cancer biology, therapy resistance, cell motility, and cytoskeletal dynamics." (PMID 36279312, 2022). "Fifteen (11.9%) cancers harbored 16 PI3K pathway mutations: PIK3CA (n = 7), AKT2 and RICTOR (n = 3 each), PTEN, PIK3C2B, and PIK3R1 (n = 1 each)." (PMID 36124727, 2022). "In terms of cancer genetics, evidence for oncogenic implications of somatic PIK3C2B alterations is scarce." (PMID 29088297, 2017). "An increasing number of studies described the involvement of the gene PIK3C2B, encoding for PI3K-C2β, in cancer." (PMID 23658859, 2013). "Treatment of MGH-CP1 does not induce p-AKT signal in mouse liver tissues, suggesting that the activation of PIK3C2B/SOX4/AKT might be tissue-specific or cancer cell line specific." (PMID 36347861, 2022). "It is well reported that PIK3C2B is located on the 1q32 locus and plays an important role in several process including cell survival, metabolism, motility, and is one of the most frequently deregulated pathways in human cancer." (PMID 35205706, 2022). "Although the primary focus of our study is on the roles of PIK3C2B in EMT and metabolic reprogramming, we have now explored its potential involvement in immune modulation and cancer stemness through gene expression analysis of public datasets." (PMID 41362647, 2025). "To further validate these findings, we examined the PIK3C2B and SOX4 transcriptional levels upon YAP/TAZ siRNA knockdown in different cancer cell lines." (PMID 36347861, 2022). "Taken together, PIK3C2B and SOX4 induction might confer resistance to TEAD inhibitors in cancer cell lines." (PMID 36347861, 2022). "We hypothesized that TEAD inhibition leads to VGLL3-mediated PIK3C2B and SOX4 induction, resulting in AKT activation, promotion of cell survival, and compromising the effects of TEAD–YAP blockade in cancer cells." (PMID 36347861, 2022). "We noticed that, although identified independently, several of these aberration hubs were connected together through protein-protein interactions and formed a protein network that included several known cancer driver factors such as MYC, EGFR, PIK3C2B, CDK1, and KDR." (PMID 29861861, 2018).
tumor (18 papers, 2013 to 2025). "Stratification by pathological staging showed progressive upregulation of PIK3C2B mRNA levels across advancing tumor stages, suggesting stage-dependent accumulation of this molecular marker." (PMID 41362647, 2025). "Its prognostic significance and role in metabolic adaptability highlight PIK3C2B as a promising therapeutic target for disrupting metastasis and enhancing tumor resilience." (PMID 41362647, 2025). "Tumor formation assays in mice using control and PIK3C2B-knockdown Lewis mouse cells showed that PIK3C2B depletion significantly reduces tumor growth in vivo." (PMID 41362647, 2025). "MDM4 is expressed in breast tissue and is amplified and overexpressed along with LRRN2 and PIK3C2B in breast and other tumor types (TCGA)." (PMID 23544013, 2013). "By conducting a cross-dataset analysis of publicly available Gene Expression Omnibus (GEO) repositories, followed by functional validation in vitro and comprehensive metabolic profiling, we demonstrate that PIK3C2B drives tumor progression by enhancing EMT and mitochondrial bioenergetic flexibility." (PMID 41362647, 2025). "Finally, two RMC-7977-resistant KPC tumours exhibited focal gains of genes encoding PI3K family members (Pik3ca in tumour 8 and Pik3c2b in tumour 7), in both cases co-occurring with gains in Myc." (PMID 38588697, 2024). "PIK3C2A and PIK3C2B were suggested to play a role in tumor progression." (PMID 34681622, 2021). "In CRC, PIK3C2B activation by upregulated IQGAP3 can promote tumor growth and metastasis." (PMID 34681622, 2021). "In addition, some mutations that were found in other types of tumor like CDK6, PIK3C2B, and ABL2 also occurred in our PDCs." (PMID 28029662, 2017). "In the late AB subpopulation we also identified mutations in PIK3C2B and RPTOR, which may sensitize the tumor to a number of drugs that target the PI3K/Akt/mTOR signaling pathways." (PMID 25729435, 2015). "Also, neither somatic mutations nor mRNA expression levels of PIK3C2B were associated with a particular tumor stage." (PMID 29088297, 2017). "The copy number amplification can also be calculated based on the values of log2 ratio and tumor cellularity, as in specimen HCC01 which had 7-copy amplification of MDM4 and PIK3C2B." (PMID 25469175, 2014). "For somatic copy number alterations, cases with high PLK3 expression not only demonstrated significant amplification peaks for PIK3C2B, PDGFRA, EGFR, and CDK4, which are defined as oncogenic drivers, but they also showed deletion peaks for tumor-suppressor genes, such as CDKN2A and CDKN2C." (PMID 39866232, 2025). "Based on the values of log2 ratios and 57% tumor cellularity, the numbers of copy gains in the amplified regions on 1q of HCC01 were estimated to be four and seven copies (including gains of MDM4 and PIK3C2B), respectively." (PMID 25469175, 2014).
bacterial infection (1 paper, 2025). "Second, the Basal.MUC16 cluster showed a significant increase (adjusted p < 0.05) in genes associated with bacterial infection (PDZD3, SFTPA2, PIK3C2B), cytokine signaling (TRIM31, SERPINB2), and apoptosis (BCL2L15, VIL1)." (PMID 39935174, 2025).
infection (1 paper, 2023). The state of being infected such as from the introduction of a foreign agent such as serum, vaccine, antigenic substance or organism. "Further studies revealed that ASFV-WT and ASFV-Δ110-9L/505-7R infection led to the differential expression of TBK1 by recruiting an autophagy activator, PIK3C2B." (PMID 37162350, 2023). "Finally, PIK3C2B, a positive regulator of autophagy, is identified as one of the key molecules mediating differential expression of TBK1 during ASFV-Δ110-9L/505-7R and ASFV-WT infection." (PMID 37162350, 2023).
myopathy (1 paper, 2017). A disease of the muscle in which the muscle fibers do not function properly. "Indeed, it was shown that the disruption of the PIK3C2B kinase resulted in a complete prevention of the myopathy phenotypes in a Mtm1 disease mouse model, and inhibition of the PIK3C2B kinase activity after appearance of myopathy symptoms promoted a striking rescue in the zebrafish model." (PMID 28294977, 2017).
respiratory system diseases (1 paper, 2025). "Previous studies showed an association between GIPR and C-reactive protein levels and ITPKA was found to be related to respiratory system diseases, while PIK3C2B was reported to be associated with lung function." (PMID 40251596, 2025).
PIK3C2B also shares sentences with these, for which no sentence is quoted: bladder cancer (3 papers); pancreatic cancer (2); breast tumor (1); colorectal cancer (1); diabetes type 1 (1); endometrial cancer (1); endometrioid ovarian cancer (1); focal epilepsy (1); gastric cancer (1); head and neck cancer (1); Hepatitis C (1); lung squamous cell cancer (1); lymphoma (1); Lynch syndrome (1); neurological disorders (1); oligodendroglioma (1); ovarian tumors (1); sarcoma (1); skin cancer (1); squamous non-small cell lung cancer (1).